IL16 (interleukin 16)
Diseases named in the same sentence as IL16 in open-access papers (continued):
Sharing a sentence is not in itself a finding about the gene and the disease.
infection (42 papers, 2005 to 2025). The state of being infected such as from the introduction of a foreign agent such as serum, vaccine, antigenic substance or organism. "As expected, PR8-infected WT mice displayed rapid loss of body weight and reached about 25–30% in the weight loss by days 8–10 post-infection, whereas IL16 KO mice maintained normal body weight, similar to the mock-infected WT mice." (PMID 34630361, 2021). "This study investigated whether IL-16 influences the activation of both osteoblasts and osteoclasts and whether targeting the anti-IL-16 antibody is a possible therapeutic strategy for preventing infection-associated bone loss." (PMID 32326301, 2020). "IL-16 inhibition could represent a new strategy for treating infection-associated bone loss." (PMID 32326301, 2020). "Perpetuation of this process is accounted for by IL-16 secretion, increasing macrophage recruitment to sites of infection." (PMID 40046384, 2025). "IL-16 attracts T-cells and other immune cells to infection or inflammation sites, a marker for immune activation in PrEP." (PMID 38983264, 2024). "We observed that ST-challenged neonatal broilers after 24 h post-infection had significant increases in pro-inflammatory cytokines- IL-6 (p = 0.0025), IL-16 (p = 0.0196), and IL-21 (p = 0.0066)." (PMID 38465263, 2024). "Consistently, IL16 deficiency markedly decreased the production of new progeny PR8 viruses at 12 and 24h post-infection." (PMID 34630361, 2021). "A549 cells were transfected with IL16-Flag-expressing plasmid or vector alone for 24h, followed by infection with PR8 virus at an MOI of 0.1." (PMID 34630361, 2021). "ISG15 expression was also decreased in IL16-expressing cells after PR8 infection, suggesting that IL16 overexpression represses type I IFN-β and ISG expression." (PMID 34630361, 2021). "The IFN-β mRNA level in the lungs was significantly higher in the IL16 KO mice as compared with WT mice at day 3 post-infection." (PMID 34630361, 2021). "In consistence, the IFN-β protein level was also higher in the lung homogenates and BALF samples of IL16 KO mice on day 3 post-infection as compared with WT mice." (PMID 34630361, 2021). "The qRT-PCR analyses showed that IL16 deficiency slightly increased IFN-β and ISG15 expression before PR8 infection, however, dramatically elevated IFN-β and ISG15 expression after PR8 infection." (PMID 34630361, 2021). "MHV68-infected cells were gated as YFP-positive cells by flow cytometry analyses and MHV68 infection resulted in elevated serum IL16 level at day 16 post-infection." (PMID 32735617, 2020). "We have shown here that MHV68 infection induces expression of unique interleukin IL16, which has recently been shown to be a blood biomarker for “pan-viral” infection-induced systemic inflammation." (PMID 32735617, 2020). "As expected, elevated concentrations of proinflammatory cytokines were observed during the acute phase of infection in the severe group, including IL-1α, IL-6, IL-8, IL-16, and TNF-α." (PMID 32990499, 2020). "Virus titers in the lungs of infected mice were quantified and the viral load was similar between MHV68-infected WT and IL16 KO mice at either day 4 or day 7 post-infection." (PMID 32735617, 2020). "We next analyzed CD8 T cell responses and did not observe significant differences for IFN-γ-expressing CD8 T cells and TNF-α–expressing CD8 T cells between WT and IL16 KO mice at day 16 post-infection." (PMID 32735617, 2020). "Both CD4 and CD8 T cells showed similar frequency in WT and IL16 KO mice after MHV68 infection, however, IFN-γ-expressing Th1 subset of CD4 T cells and CD44+ activated CD4 T cells were dramatically increased in IL16 KO mice as compared to WT mice." (PMID 32735617, 2020). "Cytokines that are upregulated during acute human infection include IL-6, IL-16, IL-17, IP-10, MCP-1, MIF, stromal cell-derived factor-1α, IL-1rα, IL-2rα, G-CSF, GM-CSF, VEGF, IL-7, IL-12p40, and IFN-α2." (PMID 31053842, 2019).
infection (continued). "Dam 2 had an increase in IL-1β, IL-2, IL-6, IL-7, IL-12, IL-15, IL-16 and IL-17A, peaking on day 14 post-infection for all but IL-12 and IL-15 which peaked on day 7 post-infection." (PMID 30657788, 2019). "By contrast IL16, a chemoattractant and modulator of T cell activation, was downregulated at both 6 and 16 h of infection." (PMID 28993767, 2017). "The expression of mRNA encoding several interleukins was also induced in the infected mouse uterus at 28 days post-infection, including Il1b, Il12a, Il12b, Il16, Il18, and Il27." (PMID 26779389, 2015). "A decrease in the percentage of IL-7(+) cells and an increase in the percentage of IL-16(+) cells in the MLN indicated that secretion of these cytokines was also altered after LP-BM5 infection." (PMID 16584110, 2005). "But when added during or early after infection, IL16 could repress HIV-1 entry and replication in macrophages and dendritic cells." (PMID 34630361, 2021). "IL-16 has previously been found to be stored in the neutrophil cytosol and released under conditions of insufficient clearance of apoptotic neutrophils that typically occur at sites of infection and inflammation." (PMID 34447377, 2021). "The infection of H. ovis and T. pyogenes also increased the IL-16 concentration in murine serum." (PMID 35224069, 2021). "Furthermore, MHV68 infection of MEFs at an MOI of 1 increased IL16 expression at 24 hr post-infection, MHV68 infection was evidenced by the detection of ORF50 expression." (PMID 32735617, 2020). "Dam 4 exhibited an increase above baseline in IL-1β, IL-2, IL-6, IL-7, IL-15 and IL-16, and similar to Dam 2, peak levels of these cytokines were on day 14 post-infection with the exception of IL-15 (day 7); by 21 dpi, most cytokines had returned to baseline or were lower than peak levels." (PMID 30657788, 2019). "The predication that IL-16C and MIF are released by secondary necrotic neutrophils is strengthened by our results that after UV light irradiation and infection with A. phagocytophilum, IL-16 and MIF release is in line with enhanced secondary necrosis, but not with apoptosis." (PMID 27551482, 2015). "These indicate that the control of the immune response of the host to toxins that is mediated by TNFα and IL-16 may represent a potent protective mechanism against infection with invasive microorganisms." (PMID 24116227, 2013). "After infection with H. pylori, the gene expressions of abundant proinflammatory cytokines in AGS cells, including TNF-α, IL-6, COX-2, IL-8, and IL-16, were upregulated significantly (p < 0.05)." (PMID 38891033, 2024). "Lower age, PCR CT, IL-6, IL-8, and IL-17A and higher IL-16, EGF, and CCL-5 appeared to provide the best univariate class separation for recurrent infection (versus recurrence-free survival and death)." (PMID 36975808, 2023). "The previous cytokine profile study following MHV68 infection shows that spleen from infected mice produces a high-level of IL6 and IFN-γ, whereas in vitro infection of naïve splenocytes induces IL16 and IL10." (PMID 32735617, 2020). "WT and IL16 KO mice were infected with 50,000 PFU of MHV68-H2bYFP viruses intranasally, splenocytes isolated from infected mice at day 16 post-infection were subjected to flow cytometry analyses." (PMID 32735617, 2020). "We further confirmed that MHV68 infection of murine primary embryonic fibroblasts (MEFs) induced IL16 expression in vitro, MHV68 infection of mice elevated serum IL16 level in vivo." (PMID 32735617, 2020). "IL-16 can be expressed by epithelial cells under inflammatory conditions and serves to chemoattract monocyptes/macrophages and CD4+ T cells to the infection site." (PMID 24465869, 2014). "Additionally, but in contrast to its HIV-suppressive properties, IL16 can enhance the replication of influenza A virus (IAV) and facilitate its infection of hosts, potentially through its repression of type I interferon beta and interferon-stimulated genes." (PMID 38848448, 2024).
infection (continued). "In response to infection, four interleukins (IL1A, IL1B, IL8 and IL16), their receptors (IL1 receptor like 1, IL1 receptor 2, IFN-lambda receptor 1, cytokine receptor like factor 1) and two acute phase proteins (Serum amyloid A 1 and 2) were differentially expressed." (PMID 38179419, 2023). "IL16 overexpression significantly reduced the level of IFN-β mRNA before and after PR8 infection." (PMID 34630361, 2021). "Furthermore, we infected WT and IL16 KO mice with a sublethal dose (8,000 PFU) of PR8 viruses and detected the IFN-β mRNA level in lung homogenates on day 2 and day 3 post-infection." (PMID 34630361, 2021). "Considering the relatively low expression level of IL6 in MEFs, BHK21 cells with undetectable endogenous IL16 were overexpressed with IL16-expressing plasmid with Flag tag or vector alone for 24 hr, followed by MHV68 infection with a high MOI of 5 or a low MOI of 0.05." (PMID 32735617, 2020). "We observed a similar frequency of YFP-positive cells in the spleens of both WT and IL16 KO mice at day 16 post-infection, suggesting that IL16 does not affect the establishment of MHV68 latency." (PMID 32735617, 2020). "Furthermore, we observed that pro-inflammatory mediators including IFN-α, IL-1β, IL-16, NF-κB, and TNF-α exhibited similar dynamic patterns, with their expression levels progressively increasing during early infection, peaking at 36 h, and subsequently declining with prolonged infection time." (PMID 41305370, 2025). "It’s worth noting that no viral load was detected in both WT and IL16 KO mice at day 9 post-infection, implicating that the infected mice might clear MHV68 from lung faster in our experimental setting than the observation by other groups." (PMID 32735617, 2020). "This was associated with increased production of disease-exacerbating proinflammatory cytokines (IFN-γ, IL-16 and TNF-α), impaired production of parasite-specific IgG, IgG1 and IgG2a antibodies and failure to sustain strong germinal centre responses during the chronic phase of infection." (PMID 25875604, 2015). "However, as we observed a change in adipoq and il16 in the absence of infection in TCRδ−/− mice, we could not draw any conclusions about the role of these genes in the response after VACV infection." (PMID 38543790, 2024). "Similarly, VEGF correlated positively with IFN-γ, IL-13 and IL-16 in BS0–II in the absence of systemic infection or substantial tangle pathology but the association was again lost in BSIII–IV and V–VI, and even sooner, in BS0–II, in cases with infection." (PMID 33723589, 2021). "Given the previous report that EBV EBNA2 could induce the expression of IL16, and human B cell lines constitutively express and secrete IL16, detection of a high level of IL16 expression in MHV68-immortalized cells implicates that MHV68 infection of B cells might induce IL16 expression." (PMID 32735617, 2020).
cardiovascular disease (6 papers, 2016 to 2025). "In cardiovascular diseases, high IL-16 serum concentrations were associated with asymptomatic carotid plaques and reduced numbers of cardiovascular events after surgery, suggesting a protective profile in atherosclerosis and the risk of cardiovascular events." (PMID 32934782, 2020). "The rs11556218 (T>G) missense mutation in exon 6 is linked to higher IL-16 levels in TG/GG genotypes, with the G allele increasing the risk of lung, oral, nasopharyngeal, gastric, and colorectal cancer, as well as osteosarcoma, endometriosis, cardiovascular disease, and SLE." (PMID 40003544, 2025). "The role of IL-16 in cardiovascular disease has rarely been reported, and the aim of this study was to examine the effects of IL-16 on DOX-induced cardiac injury and its possible mechanisms." (PMID 33958974, 2021). "However, the association between IL-16 and cardiovascular disease has not been thoroughly reported." (PMID 33958974, 2021).
neurodegenerative disease (5 papers, 2013 to 2025). A disorder of the central nervous system characterized by gradual and progressive loss of neural tissue and neurologic function. "Previous studies demonstrated upregulation of IL-16 in neurodegenerative diseases." (PMID 41255373, 2025). "Interestingly, IL-16 levels are enhanced in AD patients, confirming that the immune system and neuroinflammatory pathways may play an important role in the development and progression of this neurodegenerative disease." (PMID 32033363, 2020). "The results showed that ChT, IL-16, IL-18, and TGF-β1 increased in ischemic cerebrovascular disease (CVD) and AD, confirming that the immune system may play an important role in the development of neurodegenerative diseases." (PMID 37270510, 2023).
bacterial infection (4 papers, 2018 to 2023). "Because we detected increased IL-16 levels in patients with PJI, whether IL-16 inhibition improves GN bacterial infection-associated bone loss warrants further study." (PMID 32326301, 2020). "However, macrophage and B cells secrete IL-16 against viral and bacterial infections." (PMID 29564064, 2018). "Following bacterial infection, BDNF pretreatment reduces the expression of TNF-α, IL-16, IL-1β, and the NFκB pathways, and increases IL-10 and Trk expression." (PMID 34831151, 2021).
immune dysfunction (3 papers, 2018 to 2023). "Similarly, the quantitative and qualitative abnormalities of immunological cells and immune dysfunction in patients with ITP can be, at least in part, attributed to IL-16, suggesting the potential value of IL-16 in prognostic evaluation in ITP." (PMID 30936868, 2019). "CTLA4, a negative regulator in auto-immune diseases, participates in the pathways of CAMs and T cell receptor signalling contributing to autoimmune tissue destruction and it might exert a down-regulatory effect on TNF-α, TGF-β, IL1-β and IL16 production." (PMID 29401671, 2018).
inflammation (3 papers, 2020 to 2022). Aberrant reaction of the microcirculation characterized by movement of fluid and leukocytes from the blood into extravascular tissues. "In the present study, our results suggest that IL-16 can also regulate cardiac inflammation." (PMID 33958974, 2021). "Additionally, IL-16, TNF-β and VCAM-1 were also significantly higher in MSM-SN when directly compared to non-MSM-SN indicating GI inflammation, while exacerbated by HIV infection, is elevated in seronegative MSM." (PMID 36605218, 2022).
neurologic disease (3 papers, 2021 to 2024). "Additional to the well-established cytokines identified in CM, we discovered IL-16, which has been implicated in other neurological diseases but not in CM." (PMID 39438620, 2024). "Our findings suggest that the IL-16/CD4 signalling pathway is closely involved in the neuroinflammation of MS and other neurological disorders through the immune and CNS resident cells." (PMID 34071825, 2021).
cutaneous disorders (2 papers, 2016 to 2023). "The pleiotropic mechanism of IL-16 may suggest its role in the pathogenesis of cutaneous disorders closely associated with infiltration of CD4+ T-cells." (PMID 27788245, 2016).
mental illness (2 papers, 2023 to 2024). "Although IL-16 has been associated with psychiatric disorders and AD, this is the first study to implicate the cytokine in an experimental CM model." (PMID 39438620, 2024).
metabolic disease (2 papers, 2021 to 2024). A congenital disorder (due to inherited enzyme abnormality) or acquired (due to failure of a metabolically important organ) disorder resulting from an abnormal metabolic process. "Taken together, our results indicate that IL-16 may be involved in inflammation, lipid accumulation, and altered glucose signaling, contributing to the development of metabolic diseases." (PMID 38544694, 2024). "VSURF selected immune markers that were positively correlated with the metabolic disease score included LBP, intercellular adhesion molecule 1 (ICAM-1), interleukin-16 (IL-16), IL-12, and granulocyte-macrophage colony-stimulating factor (GM-CSF)." (PMID 34006628, 2021).
hematopoietic cancers (1 paper, 2014). "The production of IL-16 correlates with the onset and progression of various hematopoietic cancers and solid cancers." (PMID 24465869, 2014).
vascular disorder (1 paper, 2016). A general term used to describe any disease affecting blood vessels]. "IL-16 is a lymphocyte chemoattractant factor well known for its role in immune responses, but there has been scarce literature on its role in vascular disorders." (PMID 27656048, 2016).
IL16 also shares sentences with these, for which no sentence is quoted: cutaneous T cell lymphoma (5 papers); infectious disease (5); injury (3); bipolar disorder (2); Coronary Heart Disease (2); diabetic nephropathy (2); Graves disease (2); hematological malignancies (2); hepatocellular carcinoma (2); malnutrition (2); nephritis (2); osteoarthritis (2); pancreatic cancer (2); pseudoexfoliation glaucoma (2); vasculitis (2); abscesses (1); acute leukemia (1); acute respiratory distress syndrome (1); airway hyperresponsiveness (1); allergic contact dermatitis (1); allergic rhinitis (1); anemia (1); artery dissection (1); Asperger syndrome (1); atrial fibrillation (1); attention deficit-hyperactivity disorder (1); autoimmune hypothyroidism (1); autoimmune thyroid disease (1); benign tumors (1); bronchitis (1).
A further 47 diseases each share a sentence with IL16 in 1 paper.